CD34 (CD34 molecule)
Diseases named in the same sentence as CD34 in open-access papers (continued):
Sharing a sentence is not in itself a finding about the gene and the disease.
tumor (continued). "CD34-positive tumours isolated from the transplant harboured an increased number of slow-cycling BrdU-positive cells compared to primary tumour isolated from UV-induced animal." (PMID 33123267, 2020). "In this study, we used the specimens of cancer patients for immunohistochemical staining to observe the number of PD-L1+ CD34+ VECs and infiltrated immune cells inside tumor specimens." (PMID 32366856, 2020). "There were spindle-shaped tumor cells in which CD34, factor VIII, and c-myc were locally positive, suggesting radiation-induced AS." (PMID 32337612, 2020). "Immunohistochemically, tumors are often positive for at least 1 endothelial marker (factor VIII-related antigen, CD31, CD34); our tumor tested positive for CD31 immunohistochemical staining." (PMID 32312011, 2020). "Immunohistochemical studies demonstrated that negativity of SMA, desmin, β-catenin, S100, SOX10, AE1/3, EMA, CD117 and CD34 in the tumor cells." (PMID 32164724, 2020). "Pairs involving regulation of MARCO, IFITM10, and CD34 appear to function in HCC through changes involving tumor microenvironment and inflammation." (PMID 32228601, 2020). "Staining for the CD34 marker in tumor tissue recovered from mice at the end of this experiment demonstrated that CAR-expressing T cells were present at the tumor site." (PMID 33004686, 2020). "The adventitia of the intratumoural vessels is also formed by TCs/CD34+SCs (relation of the vessels with the principal cellular component in the tumour)." (PMID 32560571, 2020). "Tumor vasculature, visualized using the endothelial markers von Willebrand factor and CD34, revealed relatively low TAMRA-FP signal originating from endothelial cells." (PMID 32190011, 2020). "Vascular/peritumoral expression was identified as endothelial stains of the vessel, which was confirmed by CD34 positivity and tended to be more prominent at the tumor interface." (PMID 32703222, 2020). "As NF-kB signaling is a well-known pathway for promoting tumor angiogenesis and results showed increased total VEGF and VEGFA expression after CYLD knockout, tumor microvessel formation was investigated by IHC staining of Cd34 in xenografts." (PMID 32708712, 2020). "Patients incidentally exposed to any type of beta-blocker (i.e., cardioselective beta-blocker or wide spectrum beta-blocker) had a significantly lower intra-tumor blood vessel density, as assessed by CD34 staining." (PMID 32353988, 2020). "Similar, median OS in stromal CD34+ tumor patients was 1798 (95% CI: 1226.0–2370.0) days, while CD34‐negativity resulted in reduced median survival of 1068 (95% CI: 798.7–1337.3) days (P = 0.024)." (PMID 31760702, 2020). "The tumour cells of the removed mass were immunohistochemically positive for CD34, oestrogen, and progesterone receptors." (PMID 32787426, 2020). "In seven (10%) of the cases, CD34 staining was performed on Formalin fixed paraffin embedded (FFPE) tumour tissue." (PMID 33014128, 2020). "The MFB tumor cells show immunoreactivity for CD34, desmin, and, variably, with smooth muscle actin (SMA), estrogen receptor (ER)/progesterone/androgen receptor, CD99, B-cell lymphoma 2 (Bcl2), and CD10, and they do not express cytokeratins or p63." (PMID 30989009, 2019). "Among these altered genes, some oncogenes, such as PON2 and CD34, were downregulated, and some tumor suppressors, such as KLF6 and JUN were upregulated." (PMID 31723124, 2019). "CD34 is one of the important markers of angiogenesis, 31 while Ki67 is an important marker of tumor proliferation." (PMID 31348616, 2019). "Consecutive histological sections of four tumors covering the entire en bloc-removed tumor were immunostained with antibodies against IDH1-mutated protein (tumor cells), Ki67 (proliferating cells), and CD34 (blood vessels)." (PMID 30109401, 2019).
tumor (continued). "In the present case, the tumor was sparsely positive for CD34, which was an untypical finding of SFT, but we established the diagnosis of SFT based primarily on diffuse nuclear expression of STAT6." (PMID 31520184, 2019). "Highly interrelated nodes, such as COL1A1, COL1A2, POSTN, ADAMTS4, and CD34, have been reported to regulate the tumor microenvironment and promote the growth, angiogenesis, and invasion of malignancies." (PMID 31480381, 2019). "We also found that the mean CD34 density increased slightly with tumor aggressiveness and that vessel radius was slightly higher in the superficial tumors; however, these differences were small and must be assessed in a larger cohort." (PMID 30820651, 2019). "Through an immunohistochemical analysis, we found that the staining of Ki67, VEGF, and CD34 was increased in transplanted tumor tissues overexpressing CXCR7." (PMID 31348616, 2019). "VEGF is the strongest and most specific vascular growth factor inducing tumor angiogenesis, whereas CD34 has critical functions in intercellular adhesion and the transport and colonization of hematopoietic stem cells." (PMID 31531348, 2019). "We demonstrated that the samples with the highest ALDH activity contained an enriched CD34+ population, suggesting higher stemness and immaturity in the tumor burden." (PMID 31024847, 2019). "In tumor stroma, CD34-positive mucosal cells (brown arrow) were found intermingled with PAS-positive cells (pink arrow)." (PMID 30833656, 2019). "The oncologic outcome of GIST is more likely to be dependent on tumor biology than the type of surgical resection; physical status and CD34 are reported to be prognostic factors." (PMID 31590135, 2019). "The metastatic tumor cells expressed elevated levels of Ki-67, and STAT6, but decreased levels of CD34 relative to those in primary tumor cells." (PMID 31321477, 2019). "Immunohistochemically, tumor cells of all cases show positive for CD34, 2 of which were immunoreactive focally." (PMID 31355265, 2019). "CD34 staining showed that vascular endothelial cells were brownish yellow stained, which were most frequent at the margins of the tumor or invasive periphery." (PMID 31442259, 2019). "Microvessel density analysis in the subcutaneous tumor nodules showed that the number of the CD34+ microvessels in the GAGE7B group was higher than in the negative control group." (PMID 30871606, 2019). "In total, 699 tumor samples from 382 patients and 709 tumor samples from 388 patients were informative for CD34 and podoplanin staining, respectively." (PMID 31547460, 2019). "CD34 has over time become considered the most sensitive marker for SFTs (95–100%); therefore, to call a tumour an ‘SFT’, it should be CD34-positive." (PMID 31228959, 2019). "To characterize the features of tumor xenograft model, we performed IHC staining for cell proliferation marker PCNA, microvessel density marker CD34 and metastasis-associated marker MMP-9 in xenograft tissues." (PMID 30791942, 2019). "Tumorous cells were negative for AE1/AE3 (Dako), actin (1A4, Dako), desmin (D33, Dako) and CD34 (Qbend-10, Dako) but 80% of tumour cells were positive for epithelial membrane antigen (E29, Dako)." (PMID 31350293, 2019). "In all cases, the tumor cells were immunoreactive for CD34, desmin, smooth muscle actin (SMA), and estrogen receptor (ER) and negative for cytokeratin, p63, CD68, and beta-catenin." (PMID 30989009, 2019). "Analysis of xenograft tumor sections by Ki‐67‐, CD34‐ and TUNEL‐staining indicated that blocking HAT‐L4 expression in THP‐1 cell–derived tumors inhibited cell proliferation but not angiogenesis or apoptosis." (PMID 30843660, 2019). "When tested on mice‐bearing orthotopic tumours, the nanorobot effectively bound to the tumour vascular endothelium, as evidenced by the co‐localization with the endothelial cell marker CD34." (PMID 30592140, 2019).
tumor (continued). "The results from these analyses indicated that, despite the staining for CD31 and CD34 were higher in the tumor mucosa compared to the normal counterpart, the differences were not statistically significant." (PMID 31263680, 2019). "Immunohistochemical mean tumor vascular density was estimated by anti-CD-34 staining after tumor resection." (PMID 30893213, 2019). "Previous work has shown that CD15 labels Math1 positive, tumour-initiating granule cell precursors within Ptch1 deleted cerebellum, and in combination with CD34, can isolate demarcating neural stem cells and their derived neurons." (PMID 30657775, 2019). "Our case showed typical pathological manifestations, including more tumor cells and a “staghorn” vasculature on hematoxylin and eosin staining (HE), and was CD34-positive for immunostaining." (PMID 31764783, 2019). "To verify the IR-induced morphological microvascular changes, we examined the molecular phenotypes of the tumor vessels by immunofluorescence staining with the additional endothelial cell markers CD34 and VWF during each stage of tumor progression." (PMID 31803626, 2019). "In EBVaGC samples, we observed that EBV-positive tumor cells were involved in the formation of VM channels harboring CD34-positive and PAS-positive tumor cells." (PMID 30833656, 2019). "The tumor entity was carefully reexamined and further characterized as fascicles of spindle cells, resembling CD34-positive interstitial dendritic cells intermingled with bands of collagen." (PMID 30508695, 2019). "We performed immunohistochemistry on paraffin-embedded xenograft tumors and found that Ki-67 proliferation marker and tumor vascularization index (CD34) showed a lower expression in the Roc-A group than did the vehicle group." (PMID 31551778, 2019). "The meta-analysis showed that the CD31−/PAS+ staining is a more accurate detection method for VM+ tumor samples than CD34−/PAS+ and PAS+ staining." (PMID 31752759, 2019). "PAS staining combined with endothelial markers (CD31 or CD34) is a commonly used method for identification of tumor VM in paraffin-embedded tissue specimens and was done in 8 studies (66.7%), as well as PAS staining in 4 studies." (PMID 31752759, 2019). "Numbers of VV and LV were evaluated using immunohistochemistry detecting CD34 and podoplanin, respectively, and correlated to clinical data, biochemical recurrence (BR), and proteins analyzed in tumor cells." (PMID 31547460, 2019). "There were small differences in CD34 density, which increased slightly with tumor aggressiveness, and vessel radius which was slightly higher in the superficial tumors." (PMID 30820651, 2019). "CD34, another tumor marker, is involved in angiogenesis and is used as a quantitative indicator of micro-vessel density (MVD)." (PMID 31143705, 2019). "Immunohistochemistry on human clinical specimens revealed that CXCR4 and a tumor vasculature marker CD34 were co-distributed in tumor vessels in human OSCC specimens." (PMID 31336612, 2019). "Tumor stroma CD34-positive blood vessels appeared to be smaller in structure than normal, while the number of blood vessels was not different." (PMID 31336612, 2019). "Immunohistochemical staining showed a Ki67 index of 8% in the tumour cells, strong and diffuse positivity for CD34 and STAT6, and zonal positivity for vimentin and CD99." (PMID 31228959, 2019). "The tumor consisted of a bundle of spindle cells that were strongly positive for KIT, CD-34, and discovered on gastrointestinal stromal tumor 1 (DOG1); the positive ratio of Ki-67 was 20%." (PMID 30943904, 2019). "Immunohistochemical staining was performed for VEGF, CD34, Ki67, E-cadherin, and D2-40 to evaluate tumor malignancy." (PMID 31531348, 2019). "Highly aggressive tumor cells that formed VM were found to express CD31 or CD34, implicating the angiogenic and vasculogenic potential of the genetically deregulated tumor cells." (PMID 30833656, 2019).
tumor (continued). "Mouse skin SCC cells expressing CD34 and α6-integrin, or Sox2 are enriched in tumor-initiating or cancer stem-like cells (CSCs) relative to the bulk of tumor cells." (PMID 30874597, 2019). "Because PSMA has been reported to be present in the endothelium of tumor vessels, we used CD34 for comparison and found a significant decrease in the vascular density in ACCs compared with that of ACAs." (PMID 31040822, 2019). "We stained CD34, a marker for angiogenesis, in the primary tumor bed, surgical margin, and peritoneum by IHC." (PMID 31632482, 2019). "The elevated expression of pVEGFR2 and CD34 in LINGO2high tumor tissues and the inhibition of HUVEC tube formation by cell culture supernatant from LINGO2-silenced cell supernatant which further supports the involvement of LINGO2 in angiogenesis." (PMID 30696080, 2019). "At high magnification, in the cancer stroma near the typical blood vessels (red arrows), erythrocytes (asterisks) were seen surrounded by CD34-positive cuboidal tumor cells (blue arrows)." (PMID 30833656, 2019). "In this review, we will address modification of phenotypes and function of DCs, including cord blood CD34-derived DCs, to optimize the anti-tumor response to protect for relapses after HCT." (PMID 29867960, 2018). "Histologically, the tumor was composed of spindle-shaped cells immunohistochemically positive for c-kit and CD34, and the lesion diagnosed as a duodenal GIST." (PMID 30472631, 2018). "Tumor cells in SFTs are characteristically immunoreactive for CD34 (90 to 95% of cases) and CD99 (70%)." (PMID 30284069, 2018). "As expected, we found that the tumours from the ShNC group had a higher expression of CD34 compared with the tumours from the ShSIRT2 group by IHC staining assay." (PMID 30584257, 2018). "Many tumor cells exhibited diffuse and intense CD34 expression with ramified, CD34-expressing neural elements also apparent in regional cortex." (PMID 29701169, 2018). "The tumours expressed both glial as well as neuronal markers with expression of CD34 with increased Ki 67 ranging between 5-20%." (PMID 30774826, 2018). "CD31 and CD34 immunostaining analysis showed remarkably abundant microvessels in the tumor mass of our patient, indicating active tumor angiogenesis." (PMID 30263099, 2018). "Pathological examination revealed that the tumor was stained by S-100 and CD34, therefore the tumor was diagnosed with neurofibroma." (PMID 30408738, 2018). "Unexpectedly, significantly lower MVD/CD34 values were seen in the tumor tissues of patients with the T3–T4 tumors compared to those with T1–T2 tumors (p = 0.01)." (PMID 29748768, 2018). "Immunohistochemical analysis of tumour cell xenografts with the CD34/PAS double staining showed that VM was more prevalent in the shControl (4/6) than that in the shZEB1 group (0/6, P < .05)." (PMID 29754422, 2018). "The results showed that there were significant differences between the two groups in tumor size (P < 0.001), histological type (P = 0.013), CD34 expression (P < 0.001), and DOG-1 expression (P < 0.001)." (PMID 30445975, 2018). "This combination dose-dependently induced apoptosis and down-regulated the expression of Ki-67, VEGF and CD34 in tumor tissues." (PMID 29416826, 2018). "The identification of the over-expression of these CSC-specific markers in the CD34+/CD38− CML cells, has been associated with tumor aggressiveness, metastasis, resistance to treatment and tumor recurrence, thus defining an enhanced hCSC-like phenotype." (PMID 29423045, 2018). "Immunolabeling of CD34 and Vimentin in the tumor sections revealed that ECs and fibroblast cells were less numerous in AKT/Yap/Cre lesions." (PMID 29545603, 2018). "Immunohistochemically, the tumor cells were positive for vimentine, EMA, PR (progesterone recepters), CD34, D2–40, S100 (focal) and 2% tumor cells positive for Ki-67." (PMID 30285886, 2018). "Angiogenesis in tumor tissue was measured via microvessel density (MVD) through CD34 immunostaining." (PMID 29367676, 2018).
tumor (continued). "A statistically significant finding was seen in CD34 positivity with respect to site of the tumor (P = 0.013) and CD117 positivity with respect to the morphology of the tumor (P = 0.024); other findings however, were not statistically significant." (PMID 29996918, 2018). "To further understand the changes of FOXO3a and tumor angiogenesis in vivo, we used immunohistochemistry to detect FOXO3a and angiogenesis markers VEGF and CD34 levels in the tumor tissues." (PMID 30477221, 2018). "Recently, humanized mouse xenograft models that accept patient-derived xenografts and CD34+ cells were developed to better mimic tumor heterogeneity, the tumor microenvironment, and cross-talk between the tumor and stromal/immune cells." (PMID 30079312, 2018). "CD34+ cells located in the bulge of hair follicles were found to harbor such quiescent cells and they were identified as tumor stem cells, or tumor-initiating cells (TICs), in chemically induced skin tumors." (PMID 29896477, 2018). "To correlate the presence of VEGFR2/NRP1 trans‐complexes to vessel parameters and tumor proliferation, we immunostained tumor samples for CD34 and Ki67." (PMID 30027561, 2018). "CD34 is expressed in all endothelial cells during proliferation as well as in the G0 stage, and anti-CD34 Abs react with the largest number of endothelial cells compared to other antibodies used in studies of tumor angiogenesis." (PMID 29748768, 2018). "By analyzing the data of PASTs and GISTs from our center, we found that there was a significant statistical difference between tumor size, histological type, CD34 expression, DOG-1 expression, ulceration, and NIH grade." (PMID 30445975, 2018). "Co-staining of endothelial markers (CD31 and CD34) with ETV2 revealed preferential expression of ETV2 in GBM tumor vessels and neighboring tumor cells." (PMID 29527330, 2018). "The induction of endothelial genes (kdrl, tie2, VE-cad, and CD34) in the GBM tumor cells in both groups was then analyzed using RT-PCR or flow cytometry." (PMID 29527330, 2018). "The histological analysis of the 4 T1 allograft tumors showed that the combined treatment caused significant tumor suppression and CD31 immunostaining had a higher specificity for new vessels than CD34." (PMID 30126367, 2018). "The results showed that there was a significant difference between the two groups in tumor size (P < 0.001), histological type (P = 0.013), CD34 expression (P < 0.001), and DOG-1 expression (P < 0.001)." (PMID 30445975, 2018). "The large study including 208 GBM samples evaluated tumor angiogenesis by the expression of CD34, PDGF-C, VEGF and CD105 markers and their relation to HIF1α expression." (PMID 29662659, 2018). "Breast cancer was modelled in mice by concurrently transplanting CD34+ HSCs and tumor cells into newborn mice or engrafting both PBMCs and tumor cells into BRG mice." (PMID 29411049, 2018). "Effects on angiogenesis and proliferation were investigated using immunohistochemical stainings of tumor sections with CD34 and pH3 antibodies, respectively." (PMID 30220968, 2018). "These DCs are obtained from monocytes or CD34+ precursors and subsequently are activated with tumor Ags that will be presented to T cells in order to produce an antitumor response." (PMID 30297662, 2018). "Although without statistical significance (P= 0.72), CD34 expression level in primary tumor tissues from Hca-P-ANXA5-shRNA1 group mice on the 10th day following cell implantation showed a reduction tendency than Hca-P-ANXA5-shControl group mice." (PMID 29802377, 2018). "The efficacy of STK405759 plus DEXA or BTZ was also enhanced by reduced vascular areas and fewer branched vessels in tumor tissues, with reduced expression level of CD34 endothelial stem cell markers." (PMID 30140376, 2018). "A constant and striking feature of our tumors was intense, frequently widespread expression of CD34 by tumor cells and by ramified neural elements in the regional cerebral cortex." (PMID 27812792, 2017).